ST6GAL1 (ST6 beta-galactoside alpha-2,6-sialyltransferase 1)
Diseases named in the same sentence as ST6GAL1 in open-access papers (continued):
Sharing a sentence is not in itself a finding about the gene and the disease.
breast carcinoma (28 papers, 2008 to 2025). "Gene enrichment data analysis using both the METABRIC and TCGA breast cancer cohort suggested that higher levels of tumor ST6GAL1 transcripts were linked with metastatic progression of cancer pathways gene sets, including Hedgehog, EMT, and hypoxia." (PMID 35676533, 2022). "We also observed that tumor ST6GAL1 transcripts are significantly associated with higher intra-tumor heterogeneity scores in breast cancer patients in TCGA breast cancer cohort." (PMID 35676533, 2022). "In this study that also included MDA-MB-231 breast cancer cells, knockdown of ST6Gal1 resulted in decreased EMT characteristics in association with PI3K/AKT signaling (rather than Smads) and preservation of E-cadherin." (PMID 36106023, 2022). "The data agree with the idea that ST6GAL1 is linked to the aggressive progression of breast cancers." (PMID 35676533, 2022). "In a study by Varki’s group, deletion of the St6gal1 gene in the murine PyMT breast cancer model caused tumor cells to acquire a more differentiated phenotype, consistent with the concept that ST6Gal-I confers progenitor-like characteristics." (PMID 33148698, 2021). "In a study of 633 breast cancer patients, ST6GAL1 expression was associated with tumor stage, survival and estrogen receptor (ER)/progesterone receptor (PR)/human epidermal growth factor receptor 2 (HER2) status." (PMID 33921986, 2021). "It was found that an increase in tumor infiltrating lymphocytes (TIL) was associated with low expression of ST6GAL1 in epidermal growth factor receptor 2-overexpressing (HER2) breast cancers and by high expression of ST6GAL2 in triple-negative breast cancers." (PMID 33921986, 2021). "Importantly, elevated ST6GAL1 mRNA is associated with intra-tumor heterogeneity in breast cancer patients." (PMID 35676533, 2022). "Breast cancer cell-native ST6GAL1 is associated with metastatic progression of aggressive breast cancer, based on online KM-plotter analysis, but we also observed that high expression of cancer ST6GAL1 mRNAs is associated with a favorable relapse-free survival (RFS) in TNBC patients." (PMID 35676533, 2022). "It was identified that knocking down ST6GAL1 repressed triple-negative breast cancer cells’ viability, migration, and invasion abilities, which were restored by lowering the expression of miR-214-3p, indicating the association of this miRNA in breast cancer development." (PMID 37374977, 2023). "Altogether, our findings demonstrate ST6GAL1 is an upstream negative regulator of the Hippo pathway in breast cancer cells, providing a new insight into the regulation between N-glycosylation and Hippo signaling." (PMID 40409546, 2025). "Overall, our observations point to breast cancer cells packaging ST6GAL1 into exosome-like structures that are released into the extracellular milieu." (PMID 35676533, 2022). "The Ras pathway regulates the transcription and expression of ST6Gal1, and transfectants containing ST6Gal1-expressing cells indicate an increased adhesion to the extracellular matrix molecules in colon and breast cancer." (PMID 35744954, 2022). "In breast cancer, ST6GAL1 can promote TGFβ-induced EMT as well as maintenance of a mesenchymal state, and in pancreatic cancer, ST6GAL1-mediated sialylation can upregulate mesenchymal markers and enhance cell invasion." (PMID 36077781, 2022). "Third, breast cancer cells release bioactive exosome- and exomere-like particles, but the particles from different breast cancer lines have vastly different amounts of ST6GAL1 cargo." (PMID 35676533, 2022). "Published data already suggested that various tumor cell lines, including breast cancer cell lines, have variable levels of ST6GAL1 protein." (PMID 35676533, 2022). "Excitingly, a recent study revealed that breast cancer cells release ST6GAL1 in exosome-like vesicles, and this extracellular enzyme can remodel the cell surface and secrete glycans to promote breast cancer cell growth and invasiveness." (PMID 36077781, 2022).
breast carcinoma (continued). "In ovarian and breast cancer, ST6Gal1 mediated activation of the PI3K/AKT pathway was reported to promote invasion and EMT, respectively." (PMID 36106023, 2022). "The level of ST6GAL1 packaged and released within exosome-like particles varies depending on the breast cancer cells in our panel." (PMID 35676533, 2022). "Even though ST6GAL1 transcript abundance was diminished overall in breast cancer patients compared to matched controls, TNBC aggressive cancers have elevated ST6GAL1 mRNA compared to HER2+ and ER+ subtypes." (PMID 35676533, 2022). "Second, an extensive panel of mouse and human breast cancer cell lines had highly heterogenous ST6GAL1 expression." (PMID 35676533, 2022). "In an in vivo model of mice mammary carcinoma, decreased cancer differentiation was observed with elevated ST6Gal1 and β1-integrin." (PMID 36106023, 2022). "These and related studies have driven the idea that ST6GAL1 is a cancer-promoting factor, including breast cancer." (PMID 35676533, 2022). "Generally, elevated ST6GAL1 and dysregulated α2,6-sialylation are prominently correlated with increased malignancy, especially in the lung, colorectal, pancreatic, and breast cancers." (PMID 35676533, 2022). "Transcriptional regulation of the st6gal1 gene is complex in tumor cells, and we have noticed that human breast tumor cells have a low level of ST6GAL1 mRNA compared with mouse breast cancer cells." (PMID 35676533, 2022). "For instance, in breast cancer cells overexpression of ST6GAL1 promoted TGFβ-induced EMT through down-regulation of E-cadherin-mediated cell adhesion and up-regulation of integrin-mediated cell migration." (PMID 33921986, 2021). "Similarly, high ST6GAL1 expression in breast cancer cells and human anaplastic large cell lymphoma increased extracellular mechanism (ECM) adhesion and invasiveness." (PMID 37132100, 2023). "Here, we examine whether breast cancer cells also encapsulate functional ST6GAL1 into extracellular vesicles (EVs)." (PMID 35676533, 2022). "Furthermore, in agreement with the human breast cancer clinical cases, we observed that human breast tumor cells have very low levels (normalized 2^-delta CT) of ST6GAL1 transcripts at the steady-state culture conditions." (PMID 35676533, 2022). "Indeed, that is what we observed in some shRNA-mediated ST6GAL1-knockdown experiments in breast cancer cells." (PMID 35676533, 2022). "Furthermore, knocking down ST6GAL1 with shRNA targeted to the various ST6GAL1 sites significantly reduced the aggressive breast cancer cells’ capacity to proliferate and invade." (PMID 36547200, 2022). "Taken together, our data further support a role for ST6GAL1 in breast cancer progression." (PMID 35676533, 2022). "However, our data demonstrate the existence of an extracellular mechanistic pathway for ST6GAL1 function in breast cancer." (PMID 35676533, 2022). "In sync with the notion that ST6GAL1 is critical for breast cancer, we found that knockdown of ST6GAL1 with shRNA targeted to the different sites of ST6GAL1 significantly reduced aggressive breast cancer cell proliferation and invasive properties in a 3D cell culture setting." (PMID 35676533, 2022). "Although ST6GAL1 transcripts levels are lower in breast tumors than in normal adjacent tissues in TCGA breast cancer cohort, however among cancer patients, ST6GAL1 transcripts levels are significantly elevated in triple-negative clinical cases compared with ER+ patients." (PMID 35676533, 2022). "A recent study suggests that ST6GAL1 secreted by breast cancer cells in soluble form or as a membrane-bound form within extracellular vesicles (EVs) could complement its intrinsic activity in tumor cells, remodeling surface glycans and promoting tumorigenesis and invasiveness." (PMID 40938891, 2025).
breast carcinoma (continued). "Importantly, elevated ST6GAL1 mRNA was significantly associated with a higher tumor grade in breast cancer patients, even though ST6GAL1 expression does not appear correlated with the aggressive stage of breast cancer." (PMID 35676533, 2022). "ST6GAL1 might just provide another layer of heterogeneity in aggressive breast cancer." (PMID 35676533, 2022). "Besides melanoma, also other invasive and metastatic tumors (e.g. colon and breast carcinoma) present an aberrant expression of α2,6-sialic acids mainly because of the overexpression of ST6Gal1 sialyltransferase, which adds terminal sialic acid moieties on N-linked glycans." (PMID 26741508, 2016). "Assuming that human and mouse primers for the ST6GAL1 are similarly efficient, mouse TNBC 4T1 and breast cancer bone metastatic 4T1.2 cells have higher ST6GAL1 transcripts than ER + E0771 cells." (PMID 35676533, 2022). "In this study, the activation of PI3K/AKT was due to ST6Gal1-mediated α2,6 sialylation of Human Epidermal Growth Factor Receptor 2 (HER2), a breast cancer biomarker." (PMID 36106023, 2022). "Human TNBC breast cancer cells MDA-231, natively ST6GAL1-low and cell-surface SNA-dim, were used as targets." (PMID 35676533, 2022). "Increased ST6GAL1 expression, as we have shown in glycated BEN-MEN-1 cells, was also found in lung, colon, glioma, prostate, cervical, and breast cancer tissues." (PMID 34943806, 2021). "A recent report analyzed the relationship between the α-2,6 sialyltransferases ST6GAL1, ST6GAL2, and ST6GALNAC1 and tumor-infiltrating lymphocyte (TIL) in different breast cancer molecular subgroups." (PMID 33921986, 2021). "Related research depicts the effect of ST6GAL1 on CRC malignancy, and the potential role of ST6GAL1 in promoting tumor development is also clarified in breast cancer." (PMID 31694696, 2019). "Notably, the addition of exogenous sources of ST6GAL1 can induce a more mesenchymal and CSC phenotype of breast cancer cells." (PMID 35676533, 2022). "In some experiments, we have also noted that the level of intracellular ST6GAL1 protein does not always correspond with mRNA levels in breast cancer cells." (PMID 35676533, 2022). "Depletion of ST6GAL1 results in increased phosphorylation of large tumor suppressor kinase 1 and YAP, which induces YAP's nuclear localization, transcriptional activity, and multiple biological functions in breast cancer cells, including cell adhesion, spreading, growth, migration, and metastasis." (PMID 40409546, 2025).
pancreatic cancer (22 papers, 2017 to 2025). "Functional enrichment analysis for miRNAs upregulating CMAS revealed associations with pancreatic cancer, where sialic acid metabolism and the α-2,6-sialyltransferase ST6GAL1 have been found to be important." (PMID 40010608, 2025). "A similar, elevated expression of N-cadherin with high ST6Gal1 was associated with invasive characteristics in pancreatic cancer and HCC." (PMID 36106023, 2022). "Our analysis pointed to α-2,6-sialylation and its underlying enzyme ST6GAL1 as a potentially important glycan epitope in early pancreatic cancer based on both mouse and human data." (PMID 34634466, 2021). "Sialylation by ST6GAL1 has likewise been previously implicated in pancreatic cancer." (PMID 37643018, 2023). "ST6GAL1 has been shown to induce EMT in pancreatic cancer cells and mediate chemoresistance through sialylation of the epidermal growth factor receptor." (PMID 39937175, 2025). "α2-6 sialylation and especially ST6GAL1 have a strong tumor-promoting role in among others, pancreatic cancer and glioblastoma." (PMID 40885395, 2025). "ST6GAL1 also protects tumor cells against hypoxic stress by enhancing the accumulation of hypoxia-inducible factor 1 subunit α in ovarian and pancreatic cancer cells." (PMID 39937175, 2025). "miRNA regulation of CMAS is bidirectional, yet in pancreatic cancer, the upregulatory miRNAs prevail, which, in conjunction with ST6GAL1 expression, is responsible for the α2-6 sialic acid high phenotype in pancreatic cancer cells." (PMID 40885395, 2025). "In agreement with the cancer-promoting role of ST6GAL1, recent data revealed that ST6GAL1 is upregulated in metastatic pancreatic cancer cell models and displayed enrichment of gene networks associated with stemness, EMT, and hypoxia pathways." (PMID 35676533, 2022). "A recent study in ovarian and pancreatic cancer demonstrated that cells propagated in hypoxia exhibited an upregulation in ST6Gal1." (PMID 36106023, 2022). "In support of this notion, elevated expression of ST6Gal1 concurrently activated EGFR in the pancreatic cancer cell line Suit2, exhibiting higher invasion and elevated levels of mesenchymal markers." (PMID 36106023, 2022). "Overall, our model demonstrates that targeted deletion of ST6GAL1 has a clear protective effect against pancreatic cancer formation and progression." (PMID 34634466, 2021). "Cell culture models of pancreatic cancer and other solid tumors have demonstrated that ST6GAL1 promotes chemoresistance, cell growth, and a stem cell–like phenotype." (PMID 34634466, 2021). "The comparison of human pancreatic cancer to the adjacent normal pancreas showed statistically significant increases for ST6GAL1 and ST3GAL1 in PDAC." (PMID 34634466, 2021). "In pancreatic cancer cells, high expression of ST6GAL1 led to increased α-2,6 sialylation and activation of EGFR, as well as upregulation of mesenchymal markers and enhanced cell invasiveness." (PMID 33921986, 2021). "Consistent with both our lectin microarray data and transcriptomic analysis, we observed that α-2,6-sialic acid levels (as determined by SNA) and corresponding ST6GAL1 levels are both significantly upregulated in human pancreatic cancer." (PMID 34634466, 2021). "Our approach guided our modeling of the impact of glycosylation on pancreatic cancer, enabling the testing of ST6GAL1 in the KC mouse model and identifying it as a promoter of this disease." (PMID 34634466, 2021). "Previous studies have shown that ST6Gal1 is aberrantly expressed in various cancers, such as colon, breast, and pancreatic cancer." (PMID 30542051, 2018). "In the well-established KC (K-rasLSL.G12D/+; Pdx-1-Cre) mouse model of pancreatic cancer, a pancreas-specific deletion of ST6Gal1 delayed tumor formation and accompanying fibrosis, indicating a strong tumor-promoting role for this enzyme and for N-linked α2–6 sialic acids." (PMID 40885395, 2025).
pancreatic cancer (continued). "Furthermore, in a Genetically Engineered Mouse Model (GEMM) of pancreatic cancer with RAS activation via expression of K-RasG12D under the control of p48Cre, the loss of ST6Gal1 resulted in normal acinar area and decreased fibrosis." (PMID 36106023, 2022). "To test whether ST6 beta-galactoside alpha-2,6-sialyltransferase 1 promotes pancreatic cancer, we created a novel mouse in which a pancreas-specific genetic deletion of this enzyme overlays the KC mouse model." (PMID 34634466, 2021). "•α2,6-Sialylation and ST6GAL1 are upregulated in mouse and human pancreatic cancer." (PMID 34634466, 2021). "To determine whether ST6GAL1 plays a role in the development or progression of pancreatic cancer, we generated a novel ST6GAL1flx/flx KC mouse (ST6KC)." (PMID 34634466, 2021). "Thus, we suggest that ST6Gal1 mediates the promoting effect of fructose on pancreatic cancer metastasis." (PMID 28032597, 2017). "To determine whether ST6Gal1 upregulation by fructose substitution promotes pancreatic cancer metastasis, we investigated whether ST6Gal1 overexpression is sufficient to enhance the invasion capability of PDAC cells." (PMID 28032597, 2017). "However, larger pancreatic tumors tended to express higher levels of ST6Gal1." (PMID 28032597, 2017). "ST6GAL1 similarly promoted tumor growth in the S2-LM7AA cell model, evidenced by the reduced growth of pancreatic tumors and decreased liver metastasis in the KD cohort compared with shC controls." (PMID 37643018, 2023). "Elevated Wnt signaling, including via increased expression of regulators like WNT3A and β-catenin, was identified in RNA-sequencing analysis of metastatic subclones of pancreatic cancer cell lines S2-LM7AA and S2-013 that expressed high levels of ST6Gal1." (PMID 36106023, 2022). "To look more deeply at α-2,6-sialylation in human pancreatic cancer, we stained an orthogonal cohort of human PDAC tumors and normal pancreata for the ST6GAL1 protein and α-2,6-sialylation (SNA)." (PMID 34634466, 2021). "Schultz and colleagues reported that the sialyltransferase ST6GAL1 plays a crucial role in driving a cancer stem cell (CSC) state in ovarian and pancreatic cancers." (PMID 33921986, 2021). "The current work revealed that dietary fructose promotes the development of aggressive pancreatic cancer in Elas-CreER;Kras+/LSLG12D mice via upregulation of ST6Gal1-mediated α2,6-sialylation, thereby enhancing the metastatic potential of neoplastic cells." (PMID 28032597, 2017). "A recent report showed that ST6GAL1 increases HIF-1α accumulation in ovarian and pancreatic cancer cells grown in a hypoxic environment, and induced the expression of HIF-1α transcriptional targets, including the glucose transporters GLUT1 and GLUT3 and the glycolytic enzyme PDHK1." (PMID 33921986, 2021).